MIR5583-2 (microRNA 5583-2)
Synonyms: hsa-mir-5583-2
Gene: MicroRNA gene on chromosome 18 (39,676,719 to 39,676,777, reverse strand). Ensembl gene ENSG00000283645.
Homologues: Orthologues: chimpanzee MIR5583-2 (100% identical).